SHROOM3 (shroom family member 3)
Diseases named in the same sentence as SHROOM3 in open-access papers (continued):
Sharing a sentence is not in itself a finding about the gene and the disease.
Sepsis (1 paper, 2024). Sepsis is defined as life-threatening organ dysfunction caused by a dysregulated host response to infection. "Our findings suggest a potential novel genetic link between SHROOM3 and sepsis." (PMID 39086896, 2024).
spina bifida aperta (1 paper, 2018). "For example, whereas neither Shroom3/+ nor Lp/+ mutants have spina bifida aperta, the digenic mutants (Shroom3/+, Lp/+) have almost 40% spina bifida aperta." (PMID 30134561, 2018).
Tetralogy of Fallot (1 paper, 2024). A congenital cardiac malformation comprising pulmonary stenosis, overriding aorta, ventricular septum defect, and right ventricular hypertrophy. "As for Tetralogy of Fallot, SHROOM3 (Shroom Family Member 3, 604570) as the gene signature for such CHD subtypes has been shown to be functionally related to CHD according to a previous study." (PMID 39202774, 2024).
ureteric obstruction (1 paper, 2023). "Although tubular-specific Shroom3 knockdown in mice inhibited kidney fibrosis in a ureteric obstruction model, glomerular and podocyte-specific Shroom3 knockdown induced reversible albuminuria with podocyte foot process effacement without podocyte loss." (PMID 37509442, 2023).
xerostomia (1 paper, 2022). Dryness of the mouth resulting from reduced salivary secretion. "Another gene, SHROOM3, was suggestively associated with an increased risk of moderate to severe xerostomia." (PMID 35459784, 2022).
kidney disease (10 papers, 2011 to 2025). "Despite the strong associations of Shroom3 with kidney disease, its role in renal epithelial maintenance, repair, and development is not well established." (PMID 37313360, 2023). "Yet, an understanding of the molecular mechanisms behind the association of SHROOM3 and kidney disease remains poorly communicated." (PMID 38107159, 2023). "SHROOM3 was first identified as a gene associated with kidney disease through GWAS, whereas the molecular biology defining the cellular mechanisms was lacking." (PMID 38107159, 2023). "However, experimental evidence in animal models offering insight into potential disease associations has uncovered how subtle alterations in SHROOM3 expression can be both pathological toward kidney disease and beneficial by exerting protective effects in the kidney." (PMID 38107159, 2023). "It holds a dichotomous role in the kidney, as subtle alterations in SHROOM3 expression and function can be both pathological and protective toward kidney disease." (PMID 38107159, 2023). "Several genes, including UMOD, SHROOM3 and ELMO1 have been strongly associated with renal diseases, and some of their traits, such as eGFR and creatinine." (PMID 30359254, 2018). "Several genes, including UMOD, SHROOM3 and ELMO1 have been strongly associated with renal diseases, and some of their traits, such as eGFR and serum creatinine." (PMID 30359254, 2018). "Hence, we delineate the profibrotic Shroom3 motif and develop therapeutics for kidney disease from Shroom3 excess." (PMID 41469391, 2025). "In each case, experimental evidence shows the role of SHROOM3 being established in various signaling pathways in many developing and postnatal model systems and is providing a more thorough understanding of the normal and pathological roles for SHROOM3 in kidney disease and beyond." (PMID 38107159, 2023). "Taken together, our results describe a mild kidney disease phenotype in adult Shroom3 heterozygous null mice, suggesting that Shroom3 expression and function may be required for proper structure and maintenance of the various tubular epithelial parenchyma of the kidney." (PMID 37313360, 2023). "Altogether, these studies demonstrate that Shroom3 heterozygous null mice exhibit a mild kidney disease phenotype at 3 months that does not result in overt kidney damage or decreased kidney function." (PMID 37313360, 2023). "Shroom family member 3 (SHROOM3) also appeared to be very significant in our GAWS studies on cystatin C. It plays an important role in mammalian kidney development and human kidney disease including CKD and ESRD through estimated glomerular filtration rate based on creatinine (eGFRcrea)." (PMID 34899825, 2021).
infection (4 papers, 2022 to 2023). The state of being infected such as from the introduction of a foreign agent such as serum, vaccine, antigenic substance or organism. "EgPSC infection also caused the upregulation of Cgn, Epb41, Cldn8, Shroom3, Cask, Rab3b, Epb41l2, Csnk2b, Prkcb, and MyI12a." (PMID 36713407, 2022). "For example, several classic tight junction related genes (Ocln and Cldn4) were significantly downregulated post-infection, whereas other tight junctions-relative genes (Cldn8, Epb41L2, Prkcb, and Shroom3) were upregulated." (PMID 36713407, 2022). "EPSTI1, NACAP1, SHROOM3, C19ORF35, and MX1 as the essential features play important roles in the infection and immune response to novel coronavirus." (PMID 35620480, 2022).
cancer (3 papers, 2018 to 2025). A tumor composed of atypical neoplastic, often pleomorphic cells that invade other tissues. "We show one network consisting of 12 genes including ANKLE2, SHROOM3 and ELFN2 interacting through direct connections with VIRMA, a nuclear/cytosolic protein involved in RNA methylation/adenylation and implicated in different cancers." (PMID 35619151, 2022).
cardiac disease (1 paper, 2024). "For example, some genes, such as SNIP1 and SHROOM3, have only recently been linked to cardiac disease; so, prior to this, pathogenic variants in these genes may have been unreported or considered incidental findings in patients undergoing testing for cardiac indications." (PMID 38731073, 2024).
tumor (1 paper, 2025). "Notably, SHROOM4 is predominantly expressed in stromal cells, while SHROOM3 is more highly expressed in malignant tumor cells." (PMID 41573567, 2025).
SHROOM3 also shares sentences with these, for which no sentence is quoted: cardiovascular disease (2 papers); lung cancer (2); acute myeloid leukemia (1); asthma (1); COVID-19 (1); diabetes mellitus (1); essential tremor (1); hypertrophic cardiomyopathy (1); Hypomagnesemia (1); hypoplastic left heart syndrome (1); kidney tumors (1); melanoma (1); ovarian carcinoma (1); renal failure (1).